GJD2 (gap junction protein delta 2)
Diseases named in the same sentence as GJD2 in open-access papers (continued):
Sharing a sentence is not in itself a finding about the gene and the disease.
HIV encephalitis (1 paper, 2016). "When HIV-positive subjects were sorted according to whether or not they had HIV encephalitis (HIVE) at autopsy, the mRNAs were significantly lower than HIV-negatives in the patients without and with HIVE both (by 26 and 23 % for GAD1, 21 and 27 % for GAD2, 20 and 24 % for GJD2)." (PMID 26829944, 2016).
hyperopia (1 paper, 2022). A refractive error in which rays of light entering the eye parallel to the optic axis are brought to a focus behind the retina, as a result of the eyeball being too short from front to back. "Studies of GJD2 rs524952 gene variants showed that the AT genotype reduced the incidence of general low hyperopia in the right eye 0.26 times (95% CI: 0.067–0.971; p < 0.05) compared to AA and TT genotypes." (PMID 35885949, 2022).
liver carcinoma (1 paper, 2019). An epithelial or non-epithelial malignant neoplasm that arises from the liver. "Indeed, ALX3, GJD2, and SLC22A2, are linked to the IPA pathways 'liver carcinoma' and 'hepatobiliary system cancer'." (PMID 31695765, 2019).
schizophrenia (1 paper, 2017). A major psychotic disorder characterized by abnormalities in the perception or expression of reality. "Former evidences demonstrated a strong association of GJD2 and TJP1 with schizophrenia." (PMID 29020091, 2017).
Stroke (1 paper, 2020). Sudden impairment of blood flow to a part of the brain due to occlusion or rupture of an artery to the brain. "Interestingly, several genes such as GAD1, GJB6, GJD2, and AQP4 known to be induced or repressed by those early events of stroke are regulated in an opposite manner by PACAP which contributes to explain how PACAP protects the brain after stroke." (PMID 33551991, 2020).
ulcerative colitis (1 paper, 2016). An inflammatory bowel disease involving the mucosal surface of the large intestine and rectum. "Five (42%) of the associated genes with these CpG sites have been linked to either ulcerative colitis (FLT1 and ELTD1) or CRC (PCDHG4A, GJD2, and TP53I11)." (PMID 27006956, 2016).
genetic diseases (1 paper, 2022). "These species have highly conserved Gjd2(Cx36)/gjd1a(cx34.1)/gjd1b(cx34.7)/gjd2a(cx35.5)/gjd2b(cx35.1) proteins (mouse 98%, zebrafish 70–83%) and are well-established animal models for genetic diseases." (PMID 35262731, 2022).
peripheral nervous system disease (1 paper, 2023). "A number of these, including connexin 26 (Cx26)/GJB2, Cx29/Cx31.3/GJC3, Cx30/GJB6, Cx32/GJB1, Cx36/GJD2, Cx43/GJA1, Cx45/GJC1 and Cx47/GJC2 are expressed in the central and/or peripheral nervous system and mutations in a number of these cause central and/or peripheral nervous system disease." (PMID 37189458, 2023).
GJD2 also shares sentences with these, for which no sentence is quoted: ischemia (13 papers); epilepsy (12); diabetes (5); neuroblastoma (5); brain ischemia (3); glaucoma (3); glioma (3); retinal degeneration (3); amyotrophic lateral sclerosis (2); Cognitive impairment (2); depression (2); Insulin resistance (2); memory impairment (2); motor neuron disease (2); prediabetes (2); sudden infant death syndrome (2); tumor (2); type 1 diabetes (2); acromegaly (1); astrocytic tumor (1); autism (1); autoimmune type 1 diabetes (1); Bradycardia (1); brain cancer (1); Cerebral ischemia (1); cervix carcinoma (1); colon cancer (1); colorectal carcinoma (1); Corneal astigmatism (1); degenerative disease (1).
A further 21 diseases each share a sentence with GJD2 in 1 paper.